TNF (tumor necrosis factor)
Diseases named in the same sentence as TNF in open-access papers (continued):
Sharing a sentence is not in itself a finding about the gene and the disease.
acute liver failure (continued). "Indeed, tumor necrosis factor-α, interleukin (IL)-1β, and IL-6 levels were increased in patients with acute liver failure as well as in rodent models of acute liver failure, and are thought to contribute to cerebral edema and intracranial pressure." (PMID 25012628, 2014). "Caspase-8 has been implicated in hepatocyte apoptosis in liver injury, anti-caspase-8 could effectively inhibit apoptosis of Hepa 1-6 cells induced by TNF-α and caspase-8 small interfering RNA prevents mice from acute liver failure." (PMID 22266786, 2012). "Elevated serum levels of several cytokines, including TNF-α, sTNF-αR1, sTNF-αR2, IL-2, IL-2R, IL-4, IL-6, IL-8, IL-10, and interferon-γ, have been described in patients with ACLF, whereas other studies reported normal TNF-α levels in patients with ACLF or acute liver failure." (PMID 17156425, 2006). "In human acute liver failure, monocyte derived TNF-α has a clearly described protective role, with low TNF-α levels due to monocyte exhaustion resulting in poor outcomes." (PMID 32321925, 2020). "Induction of acute liver failure in mice using LPS/d-galactosamine led to increased expression of KC TNF and decreased H3K27Me3 and EZH2 occupancy at the TNF promoter in KCs." (PMID 33574817, 2020). "The aim of the present study was to investigate the role of Rhcg in the brain in acute liver failure (ALF) and the effect of TNF-α on Rhcg expression." (PMID 30134917, 2018). "In our acute liver failure animal models, TNF-α level in liver tissue increased, suggesting that TNF-α may partake in liver damage." (PMID 40333907, 2025). "In addition, in acute liver failure, inhibition of miR-15b reduced the hepatic apoptosis via BCL2 regulation and TNF-α production." (PMID 25323448, 2014). "In the largest review of reported cases, HBV reactivation following anti-TNF therapy occurred in 39% (35/89) of HBsAg positive individuals, including 4 fatal cases of acute liver failure, and in 5% (9/168) of HBsAg-negative and anti-HBc-positive individuals, including 1 fatal case." (PMID 25875198, 2015).
Multiple Organ Failure (69 papers, 2006 to 2026). A progressive condition usually characterized by combined failure of several organs such as the lungs, liver, kidney, along with some clotting mechanisms, usually postinjury or postoperative. "On the other hand, systemic administration of high TNFα doses has been associated with significant side effects, including hypotension and multiple organ failure." (PMID 38051374, 2024). "TNF-α induces systemic activation of complements and procoagulant proteins, mediating the initiation and progression of multiple organ failure." (PMID 33743681, 2021). "Hemorrhagic shock leads to an uncontrolled inflammatory response in which many interleukins (IL), tumor necrosis factor (TNF), and other inflammatory mediators are released, eventually causing multiple organ failure (MOF)." (PMID 34712822, 2021). "SARS-CoV-2 combined with ACE2 stimulated macrophages and monocytes to release proinflammatory cytokines, including IL6, NF-kB, and TNF-α, leading to inflammation-derived injurious cascades and then to multiple organ failure." (PMID 34335247, 2021). "In S. aureus sepsis, cytokine storm (highly elevated TNF, IL-1, and IL6) induced by S. aureus superantigens, Lpp, PGN, and other components causes hyperinflammation, DIC, multiple organ failure, and later death." (PMID 33546401, 2021). "Cytokine storm refers to the phenomenon where a variety of cytokines in body fluid, such as TNF-α, IL-1, and IL-6, are produced rapidly after an organism is infected and is an important cause of ARDS and multiple organ failure." (PMID 32903363, 2020). "In particular, a correlation between serum IL-6 and TNF-α level and multiple organ failure has been reported." (PMID 32079307, 2020). "Concentrations of IL-6 are elevated in conditions such as surgical stress, trauma, multiple organ failure, and septic shock and peak after TNF-α and IL-1." (PMID 32232117, 2020). "LPS results in the overexpression and release of proinflammatory cytokines, including tumor necrosis factor-α (TNF-α), interleukin-1β (IL-1β), and interleukin-6 (IL-6), which contribute to LPS-induced multiple organs failure including myocardial depression." (PMID 31315617, 2019). "TNF-alpha, IL-8, IL-10, and IL-1ra mRNA levels were quantified by RT-qPCR and compared to multiple organ failure, 30-day survival, and the induction of therapeutic hypothermia (TH)." (PMID 29445259, 2017). "These previous studies, including ours, support the present findings of the role of IL-1β in trypsin upregulation in combination with IL-6 and/or TNF-α, and also on the role of trypsin in the induction of various signal transductions in multiple organ failure." (PMID 27714503, 2017). "TNF-α is believed to play an important role in the pathogenesis of endotoxin-induced multiple organ failure." (PMID 24392457, 2013). "Previous studies have demonstrated that the expression of iNOS is stimulated by proinflammatory cytokines, including IL-1β and TNF-α, which contribute to tissue damage and multiple organ failure." (PMID 23573152, 2013). "The frequency of TNFα genotypes was also significantly different between multiple organ failure patients and controls." (PMID 21860543, 2011). "It has been reported that the histamine and TNF-α released from activated the intestinal mucosal mast cells (IMMC) play an important role in the development of multiple organ failure." (PMID 23674977, 2006). "This activation triggers inflammatory gene expression characterized by excessive cytokine release, including tumor necrosis factor-alpha, interleukin-1 beta, and interleukin-6, ultimately resulting in widespread tissue damage, increased vascular permeability, and multiple organ failure." (PMID 40941711, 2025). "The presence of SNPs in the promoters of TNFA and IFNG genes also modulates their abnormal expression of TNF-α and IFN-γ, characterizing cytokine storms in response to pathogenic insults and ultimately leading to multiple organ failure." (PMID 39518964, 2024).
Multiple Organ Failure (continued). "During COVID-19 infection, tumor necrosis factor (TNF) plasma concentration elevates, which may cause morbidity or even death from multiple organ failure." (PMID 38131979, 2023). "A likely explanation for the shock and multiple organ failure might be that the increased amount of TNF-α triggers a considerable elevation in NO synthase activity, leading to multiple organ failure." (PMID 28533521, 2017). "This indicates that multiple organ failure in SAP is associated with direct damage to the pancreas as well as circulatory disturbances, and endothelial injury and increased apoptosis are associated with the increased expression of TNF-α." (PMID 25688263, 2015). "TNF-α may play a role in the initiation or progression of multiple organ failure during endotoxic shock, and it has also been shown to be a particularly important mediator of acute lung injury." (PMID 24963491, 2014). "Previous studies show that elevated levels of TNF-α and IL-1 might be an important factor in the occurrence of multiple organ failure after thermal injury; therefore, the increase of the TNF-α and IL-1β circulating levels after a burn indicated a poor prognosis." (PMID 30837795, 2019). "However, if NKT cells are inadequately activated, septic shock or multiple organ failure via TNF-α/Fas ligand (FasL) may occur." (PMID 31137499, 2019). "Several studies have demonstrated that pro-inflammatory cytokines, including IL-1, IL-6, interferon-γ (IFN-γ), and tumor necrosis factor (TNF), are excessively released during AIV infection, leading to tissue damage and multiple organ failure." (PMID 40076601, 2025). "High amounts of circulating pro-inflammatory TNF-α, the characteristic manifestation of FHF, ultimately induce multiple organ failure." (PMID 32158448, 2020). "Clinical studies revealed that the levels of TNF-α, IL-1β, and IL-6 in BALF and plasma of patients with ALI/ARDS increased and were correlated with the pathogenesis of multiple organ failure." (PMID 23586067, 2013). "High circulating and tissue levels of proinflammatory cytokines, such as tumor necrosis factor-alpha (TNF-α) and interleukin-6 (IL-6), appear to contribute to the development of a systemic inflammatory response that produces or aggravates lung damage and may lead to multiple organ failure." (PMID 20199666, 2010). "Indeed, as soon as a pathogen is detected by the immune system, pro‐inflammatory cytokines will be released, and, an early release of TNF‐α by macrophages (through TLR4 pathway) may induce disseminated intravascular coagulation, hypotension and multiple organ failure." (PMID 34288548, 2021).
prediabetes (69 papers, 2012 to 2025). "Elevated levels of IL-18, NFATC4, TNF-α, and IL-6 were all associated with significantly higher odds of prediabetes compared to healthy controls (all P < 0.001)." (PMID 40027364, 2024). "Elevated IL-18, IL-6, and TNF-α levels were associated with significantly increased prediabetes odds in univariate analysis (all P < 0.001)." (PMID 40027364, 2024). "IL-18, IL-6, and TNF-α were selected as the focus of this study due to their strong association with the chronic inflammation underlying prediabetes and its progression to cardiovascular disease." (PMID 40027364, 2024). "IR is a hallmark of prediabetes and can result from proinflammatory cytokines such as TNFα and IL1β causing impaired insulin signaling in insulin target organs." (PMID 26317345, 2015). "However, it is essential to investigate other inflammatory factors, such as IL-10, TNF-α, and adipokines, which are implicated in prediabetes." (PMID 38004306, 2023). "miR-34a showed consistent elevation across obese prediabetes cohorts, targeting TNFα, procalcitonin, and Wnt signaling modulators such as SFRP4." (PMID 41400625, 2025). "This systematic review and meta-analysis demonstrate that probiotic and synbiotic supplementation effectively reduces inflammatory markers, including CRP, IL-6, and TNF-α, in adults with prediabetes and T2DM." (PMID 41022286, 2025). "Another study demonstrated elevated serum TNF-α levels and reduced serum IL-10 levels in patients with prediabetes and patients with T2DM and PDN compared with controls without DM." (PMID 39408723, 2024). "It was found that higher levels of inflammatory markers (IL-18, TNF-α, IL-6) and increased NFATC4 gene expression were associated with a greater risk of prediabetes compared to healthy controls." (PMID 40027364, 2024). "Receiver operating characteristic (ROC) curve analysis identified IL-18 and NFATC4 as the most promising biomarkers for predicting prediabetes, followed by TNF-α and IL-6." (PMID 40027364, 2024). "In the prediabetes group, IL-1β, IL-6, IL-8, TNF-α and MAPK were significantly higher in those with Vit D insufficiency and deficiency groups." (PMID 38136648, 2023). "The prediabetes stage is associated with an increased level of inflammatory markers, namely, CRP, IL-6, and TNF-α." (PMID 38068801, 2023). "This article reports that patients with prediabetes who received FCE had a desirable outcome of a reduction in serum TNF-α for a long period." (PMID 35447934, 2022). "Profound elevation of TNF-α in T2DM was found compared with prediabetes or the healthy group, but it showed an insignificant rise when comparing prediabetes with the healthy." (PMID 35311231, 2022). "Our results strongly indicate that FCE derived from Corbicula fluminea can suppress the release of TNF-α in patients with prediabetes." (PMID 35447934, 2022). "The levels of IL-6 and TNF-α in the single crown group of prediabetes were 138 pg/mL and 98 pg/mL, respectively." (PMID 36557041, 2022). "Herein, we have further evaluated the effect of FCE in suppressing the TNF-α concentration in clinical trials, and the results indicate that FCE significantly inhibits TNF-α and provides long-term protection in patients with prediabetes." (PMID 35447934, 2022). "In this study, we firstly revealed the differences of adiponectin, nesfatin-1, IL-6, and TNF-α between prediabetes and T2DM or healthy individuals in Chinese population." (PMID 35311231, 2022). "FCE intervention effectively reduced serum TNF-α and persistently sustained the effects for half a year in patients with prediabetes." (PMID 35447934, 2022). "In the splinted crown subgroup of prediabetes, the value of IL-6 was 154 pg/mL and that of TNF-α was 115 pg/mL." (PMID 36557041, 2022). "Prediabetes stage is associated with the increase in the level of inflammatory markers, that is, CRP, IL-6 and TNF-α." (PMID 33211181, 2021).
prediabetes (continued). "Researchers used the I-arginine test to compare the endothelial function and to measure the levels of TNF-α between healthy subjects and patients with prediabetes after a high-fat diet." (PMID 33921168, 2021). "A study found a reduction of TNFα concentration in prediabetes patients supplemented with 45 g/day high-amylose maize for 12 weeks." (PMID 34354689, 2021). "In contrast, α-Toc was modestly positively correlated with TNF-α (r = −0.20, p < 0.01 in prediabetes, r = −0.19, p < 0.05 in NGT)." (PMID 32509152, 2020). "Cytokines play an important role in the procedure of β-cell failure and IL-1β; TNF-α and IL-6 have been shown to diversely regulate pancreatic β-cell function leading to inflammation in prediabetes patients." (PMID 30039349, 2019). "After the adjustment for waist circumference the significance persistent for IL-4, IP-10, TNF-α, RANTES, CD40L and VEGF, indicating that inflammation is an independent hallmark in prediabetes." (PMID 30143687, 2018). "Several population-based studies have confirmed that low-grade systemic inflammation and increased levels of markers of inflammation such as hs-CRP, IL-6, tumor necrosis factor-α, and IL-1RA are already present in those with prediabetes." (PMID 28911155, 2017). "Elevated levels of acute-phase proteins, such as high-sensitivity C-reactive protein (hs-CRP) and tumor necrosis factor-α are often already present in those with prediabetes and are predictive of future type 2 diabetes and cardiovascular disease (CVD) events." (PMID 28911155, 2017). "Additionally, TNF‐α levels were significantly higher in patients with prediabetes compared to T2DM (p = 0.007)." (PMID 39829127, 2025). "Research indicates that individuals with prediabetes exhibit elevated levels of multiple inflammatory markers, including resistin, interleukin-6 (IL-6), TNF-α, interleukin-1β (IL-1β), and monocyte chemoattractant protein-1 (MCP-1), in their serum along with high fasting blood glucose levels." (PMID 39634176, 2024). "The Health, Aging, and Body Composition study demonstrated that dysglycemia is associated with inflammation, as expressed by an increase in CRP, tumor necrosis factor-alpha (TNF-a), and interleukin-6 (IL-6) levels among older people (70–79 years) with prediabetes and DM." (PMID 39335474, 2024). "Moreover, the modulating effects of probiotics or synbiotics on inflammation (CRP and TNF-α levels) were more pronounced in patients with T2DM compared to individuals with prediabetes." (PMID 36239789, 2023). "This review suggests that the physical activity promotion program may reduce the level of leptin and IL-6, but whether there is any effect on the level of adiponectin, CRP, and TNF-α in individuals with prediabetes is uncertain." (PMID 38068801, 2023). "However, the variation of TNF-α and IL-6 levels in prediabetes and their comparison with T2DM and the healthy group have not been disclosed." (PMID 35311231, 2022). "Nonetheless, previous studies suggested that pro-inflammatory diet could promote low-grade inflammation that is characterized by elevated pro-inflammatory markers, namely, CRP, TNF-α, and interleukin-6 which may lead to prediabetes and IR." (PMID 35250879, 2022). "This review suggests that physical activity promotion programme may reduce the level of leptin and IL-6, but it is uncertain whether there is any effect on the level of adiponectin, CRP and TNF-α in individuals with prediabetes." (PMID 33211181, 2021). "In conclusion, our findings indicate that dietary intake of non-α-tocopherols might protect against cellular aging markers mediated by TNF-α in prediabetes." (PMID 32509152, 2020). "The patients with prediabetes showed higher serum levels of TNF-α than controls with normoglycemia." (PMID 30867412, 2019).